IL33 (interleukin 33)
Diseases named in the same sentence as IL33 in open-access papers (continued):
Sharing a sentence is not in itself a finding about the gene and the disease.
asthma (continued). "Interleukin-33 (IL-33) is associated with multiple diseases, including asthma, rheumatoid arthritis, tissue injuries and infections." (PMID 24586149, 2014). "Meanwhile, IL-33 is another powerful inducer of allergic inflammation which has been found highly expressed in Th2-associated diseases including asthma, allergic conjunctivitis and rhinitis." (PMID 24699261, 2014). "These activities suggest potential roles for IL-33 in Th2-associated immune responses, and thus IL-33 is thought to be closely associated with allergic inflammatory diseases, including asthma." (PMID 25061262, 2014). "ST2/IL-33 overstimulation has been implicated in allergic and autoimmune diseases such as arthritis, airway hyperactivity and asthma, demonstrating an important role of ST2 in the development of Th2-dominant inflammatory pathologies." (PMID 23585867, 2013). "In the third part of this study, we evaluated the role of IL-33 in the inflammation associated with an acute exacerbation of asthma." (PMID 23936781, 2013). "Several lines of evidence demonstrate the pathogenic role of IL-33 in numerous immune and inflammatory diseases, such as asthma, rheumatoid arthritis, multiple sclerosis and anaphylaxis." (PMID 23634226, 2013). "Early genomic studies indicated that polymorphism in several genes related to PRRs, such as TLRs or NODs, is related to asthma, while a larger genome-wide association study (GWAS) additionally identified IL-33, ST2, and TSLP (thymic stromal lymphoprotein) as being important in asthma." (PMID 39861052, 2025). "Recent work has shown that another epithelial-derived alarmin, called TL1A, can act with IL-33 to increase IL-9 production by ILC2s, which then becomes pathogenic, suggesting that IL-9 might represent an interesting target in asthma." (PMID 41145900, 2025). "Whether or not IL-33 and AM survival are linked has yet to be described, although IL-33 has been shown to activate AMs in a mouse model of asthma." (PMID 41190814, 2025). "Importantly, a greater presence of Tc2 cells (Tc cells producing type 2 mediators) is associated with asthma exacerbations, thus highlighting a potential role of IL-33 in these episodes." (PMID 40723867, 2025). "Several studies have analyzed the IL-33 association with asthma." (PMID 40723867, 2025). "Moreover, in keeping with an etiological role in this disease, single nucleotide polymorphisms in the IL-33 gene predispose to the development of asthma." (PMID 41246133, 2025). "Importantly, our unbiased proteomic analyses revealed that IL-9, a type 2 cytokine associated with allergic inflammation and asthma, was the most induced protein in ILC2s costimulated with IL-33 and TL1A." (PMID 38597952, 2024). "A role for IL-33 in human airway disease pathogenesis was established by a series of large-scale genome-wide association studies (GWAS) reporting a link between asthma and single-nucleotide polymorphisms (SNPs) flanking the IL33 and IL1RL1/ST2 (IL-33 signaling receptor) loci." (PMID 38456508, 2024). "IL-33 levels are associated with the clinical severity of asthma, and genetic variants of IL-33 have been linked to susceptibility to allergic rhinitis and asthma risk." (PMID 39559705, 2024). "Poor antigen clearance results in pro-oxidant pathway activation and airway epithelial damage and may predispose PCD patients to DUOX1- and IL33-mediated asthma." (PMID 39337527, 2024). "Additionally, the presence of asthma and level of IL-33 were associated with increased frequency of ILC2 cells in BAL." (PMID 39200943, 2024). "Moraxellaceae-dominant microflora caused a higher risk of asthma worsening as well as eosinophil activation, and in vitro experiments showed that Moraxellaceae induced epithelial cell damage and elevated the levels of the inflammatory factors IL-33 and IL-8." (PMID 37485534, 2023). "In addition, people carrying a loss-of-function mutation of IL33 have reduced blood eosinophil counts and are protected from asthma." (PMID 37607012, 2023).
asthma (continued). "Increased IL-33 expression is associated with severe and refractory asthma." (PMID 37607012, 2023). "Moreover, previous studies have shown a direct association between IL-33 and inflammatory diseases such as asthma, inflammatory bowel disease(IBD), chronic obstructive pulmonary disease(COPD), myocardial infarction and atopic dermatitis." (PMID 37153553, 2023). "Consequently, blocking IL-33 has been shown to inhibit the T2 type inflammatory pathway, which is the most common pathogenic pathway of asthma." (PMID 38082335, 2023). "Indeed, IL-33 blockade led to a lower incidence of loss of asthma control and improved lung function." (PMID 37907612, 2023). "However, Tc cells can also respond to asthma-associated type-2 activation signals, including IL-33 and IL-411." (PMID 37612281, 2023). "Clinical research results indicate that IL-33 is associated with the severity of asthma." (PMID 38082335, 2023). "High IgE levels may also be associated to T2 high asthma, and like FeNO the T2 high-associated increased total IgE levels decreased during inhibition of alarmin IL-33, IL-13 and dual IL-4 and IL-13 signalling." (PMID 40980110, 2023). "Interestingly, loss-of-function mutations in the IL33 gene in humans show reduced blood eosinophil counts and lower susceptibility to Th2-driven diseases such as asthma." (PMID 35371073, 2022). "The major cellular contributors of multiple asthma-associated inflammatory mediators, such as Il33, Hmgb1, Retnla, and Ager were identified, and a cluster of novel allergy-associated molecules, such as Chia1, Nnat, and Nr4a1 were found in different lung epithelial cells." (PMID 35627266, 2022). "IL-33, indirectly activating eosinophils, and associated with chronic inflammation and airway remodeling in asthma, was found lower in our children with normal weight and asthma." (PMID 36291398, 2022). "Given that 60–80% of asthma exacerbations in adults and 90% of wheezing episodes in children are caused by HRVs, the impact of IL-33 to promote HRV infectivity of MCs may play an important role in the worsening of asthma symptoms." (PMID 36366528, 2022). "A rare loss of function variant in IL33 has been shown to be protective against asthma." (PMID 36685501, 2022). "With genome-wide association studies demonstrating associations between single-nucleotide polymorphisms of the TSLP and IL-33 gene and risk of asthma, it will be important to understand which subsets of asthma patients will benefit most from anti-alarmin therapy." (PMID 35406669, 2022). "In contrast to SNPs evaluated in the previous studies, a whole genome sequencing project in Iceland found the IL-33 SNP rs146597587 was associated with lower eosinophil counts in children, suggesting expression of this SNP provides protection from developing asthma." (PMID 36292755, 2022). "Furthermore, IL-33 enhances type 2 cytokine secretion by cells associated with asthma pathogenesis including MCs, basophils, T cells and type 2 innate lymphoid cells (ILC2s)." (PMID 36366528, 2022). "IL-33, like IL-25, has been found to be associated with virus-associated asthma exacerbations." (PMID 36311787, 2022). "IL-33 is also implicated in the disease phenotypes of asthma, atopic dermatitis, and psoriasis." (PMID 35159396, 2022). "The combination of variants may lead to a particular type of asthma such as IL33 high, which then may be amenable to therapy targeting IL33." (PMID 35386986, 2021). "Genome-wide association studies (GWAS) have implicated the IL33 locus in asthma, but the underlying mechanisms remain unclear." (PMID 34675193, 2021). "IL-33, an IL-1 family cytokine and typically linked with type 2 inflammation was associated with reduced sensitivity to corticosteroid therapy in asthmatic children and the animal models of asthma." (PMID 34484177, 2021).
asthma (continued). "Our data demonstrate that asthma-associated variants at the IL33 locus mediate allele-specific regulatory activity and IL33 expression, providing a mechanism through which a regulatory SNP contributes to genetic risk of asthma." (PMID 34675193, 2021). "IL-33 is associated with pulmonary infection and chronic diseases like asthma and COPD, but its role in COVID-19 is unknown." (PMID 33837219, 2021). "In addition, genetic studies in humans have demonstrated that the mutation of one allele, that results in loss of function of IL-33, reduces the number of eosinophils in the blood and protects against asthma." (PMID 35011670, 2021). "Early life exposure to allergens, oxygen supplementation and viral infections may increase the risk for asthma development later in life through IL-33-induced innate memory." (PMID 34048460, 2021). "As an example to appreciate the effect size that we are detecting, the most significant associated asthma variant on chromosome 9 near the IL33 gene has a P value of 1.25E−56 and an OR of 1.13, which is the result of allele frequencies of 0.73 in cases and 0.75 in controls." (PMID 34103634, 2021). "Moreover, in comparison with T2-low asthma, type 2 disease is associated with higher IL-33 serum levels." (PMID 34572294, 2021). "Our study suggests that PM is a risk factor in promoting pediatric asthma exacerbation, in which IL-33 might be a promising target." (PMID 34254951, 2021). "We asked whether IL-33 and leptin, both expressed in the airway, might interact with each other and contribute to the pathogenesis of obesity-associated asthma." (PMID 34074279, 2021). "Collectively, these data characterize a 5 kb region that harbors both asthma-associated SNPs and marks of regulatory activity that could modulate IL33 expression through long-range chromatin interactions." (PMID 34675193, 2021). "Moreover, single nucleotide polymorphisms in IL-33 have been observed in human asthma patients, and increases in IL-33 and IL-33 receptor expression (ST2) occur in individuals with chronic obstructive pulmonary disease and obstructive sleep apnea." (PMID 33376451, 2020). "The role of IL‐33 in asthma has been identified in genome‐wide association studies." (PMID 32566227, 2020). "The functional role of IL-33 in T2 immunity-associated allergic responses and asthma has been extensively investigated in vivo and numerous studies have shown that inhibition of IL-33/ST2 signaling attenuates T2 inflammation in murine models of allergic asthma." (PMID 33255348, 2020). "Whether IL-33 regulates CD146 in the EMT process associated with asthma airway remodeling is still largely unknown." (PMID 32793232, 2020). "A recent publication describes a rare loss‐of‐function mutation in IL‐33, protecting from asthma." (PMID 33133517, 2020). "In humans there are several single-nucleotide polymorphisms (SNPs) upstream of the IL-33 gene, which are associated with asthma prevalence; however, the functional consequences of these SNPs is largely unknown." (PMID 33072128, 2020). "In particular, we identify that a functional haplotype consisting of several polymorphisms encoding 4 amino acid changes (increased asthma risk, Ala433/Gln501/Thr549/Leu551) and present in ~50% of the European population enhanced NF-κB activity after IL-33 stimulation." (PMID 32324168, 2020). "IL-33 deficiency reduced lung resistance in the murine model of asthma." (PMID 32793232, 2020). "In addition, a loss-of-function mutation in the Il33 gene has been reported to be associated with lower number of blood eosinophils and a reduced risk of developing asthma." (PMID 32582171, 2020). "A review addressed the current literature describing the role of IL-33 -responsive immune cells that may explain susceptibility to allergic sensitization at a young age and the association between genetic variants of IL-33 and asthma in humans." (PMID 33292572, 2020).
asthma (continued). "Epithelium-derived cytokines, including TSLP and IL-33, have a pivotal role in the development of allergic response at gut barrier surface and have been linked to the pathogenesis of type 2 inflammatory diseases, including food allergy and asthma." (PMID 33679694, 2020). "Finally, IL-33 is closely associated to asthma, since it is increased in asthmatic patients and was shown to potentiate airway hyper-reactivity." (PMID 30949175, 2019). "As a Th2 promoting cytokine, IL-33 has been implicated in asthma pathogenesis." (PMID 31293586, 2019). "Indeed, several studies have demonstrated that mast cells are a major ST2-expressing cell type and are associated with the IL-33-related development of asthma." (PMID 31197082, 2019). "In addition, Rhinovirus infection which is an important risk factor for asthma exacerbations, increases IL-33 levels in nasal lavage of asthmatic patients." (PMID 31490928, 2019). "Several genome wide association studies have found SNPs in genes encoding IL-33 or its receptor ST2 (IL1R1) to be risk factors for eosinophilic asthma, early childhood onset asthma, and severe forms of the asthma Airway biopsies of asthmatics have higher IL-33 mRNA expression than healthy subjects." (PMID 31490928, 2019). "Interestingly, multiple genetic studies demonstrated the association of numerous single nucleotide polymorphisms (SNPs) in the IL33 locus with asthma susceptibility and even with formation of certain phenotypes of respiratory diseases." (PMID 30544846, 2018). "Based on the available data, we hypothesized that the rs928413(G) allele may be mechanistically linked to asthma susceptibility via transcriptional activation of the IL33 gene." (PMID 30257479, 2018). "IL33 c.487-1G > C was associated with a protective effect of asthma in each data set." (PMID 29691411, 2018). "Thus IL-33 seems to be closely associated with allergic inflammatory diseases, including atopic dermatitis and asthma." (PMID 29713240, 2018). "However, we observed that partial loss of PTRF led to an increased level of IL-33 in BALF in OVA-induced asthma model, which led to excessive type 2 immune responses." (PMID 29977243, 2018). "To further replicate the association of IL33 c.487-1G > C with asthma, we examined the association of IL33 c.487-1G > C with asthma in individuals from three additional studies (Partners Biobank, the Vanderbilt eMERGE network, and the Women’s Genome Health Study)." (PMID 29691411, 2018). "Moreover, a rare loss of function mutation in IL-33 gene has been shown to cause reduced numbers of eosinophils in blood and to protect against asthma." (PMID 30233590, 2018). "Interestingly, a rare variant in IL-33, rs146597587-C allele, is associated with lower eosinophil tallies, and reduced risk of asthma and allergic rhinitis in Europeans." (PMID 29987222, 2018). "Accordingly, elevated expression of IL33 in the airway and lung epithelium is supposed to be associated with the maintenance of mucosal inflammatory conditions and the aggravation of pathological changes during asthma." (PMID 30257479, 2018). "Finally, we note that the same rare IL33 variant was recently shown to associate with reduced eosinophil count and protection from asthma in the Icelandic population." (PMID 28787443, 2017). "Other robust asthma associations have been found in and near IL33, TSLP, and IL1RL1, supporting the notion that epithelial cell-derived cytokines play a critical role in promoting the differentiation and activation of T helper 2 (Th2) cells in asthma pathogenesis." (PMID 28774304, 2017). "These include a rare p.Arg172Gly missense of plasminogen associated with higher platelet count, lower D-dimer concentration and lower platelet reactivity and a rare splice acceptor variant of IL33 associated with lower eosinophil count and lower risk of asthma and allergic rhinitis." (PMID 28787443, 2017). "IL33 has been long associated with asthma but also with allergic rhinitis in murine models." (PMID 28598986, 2017).
asthma (continued). "We therefore infer that asthma risk is mediated through IL-33." (PMID 28273074, 2017). "As AD is closely associated with asthma, IL-33 could also be secondarily involved in skin-mediated asthma development." (PMID 28490737, 2017). "Together these data demonstrate that rs146597587-C is a loss of function mutation and support the hypothesis that IL-33 haploinsufficiency protects against asthma." (PMID 28273074, 2017). "This suggests that IL33 may influence asthma risk in part by controlling blood eosinophil count, but also through currently unknown additional biological pathways." (PMID 28787443, 2017). "Importantly, large population genome wide association studies have shown that small nucleotide polymorphisms (SNPs) involving IL33 and its receptor are associated with increased asthma susceptibility." (PMID 28959799, 2017). "Interestingly, GWAS have associated IL33 common non-coding variants with risk for asthma, allergic rhinitis, and endometriosis." (PMID 28787443, 2017). "Interleukin 33 (IL-33) represents a potential link between the airway epithelium and induction of Th2-type inflammatory responses associated with the development of asthma." (PMID 28652606, 2017). "Since eosinophils are known to play a key role in inflammation of the airway in asthma we used high-coverage sequencing to search for novel sequence variants affecting eosinophil counts at the well established asthma loci, the IL33 and IL1RL1 loci, and tested their effects on asthma." (PMID 28273074, 2017). "Similarly, genetic studies have identified a large number of asthma susceptibility genes that are differentially expressed in the airway epithelium in asthma including interleukin 33 (IL33) and thymic stromal lymphopoietin (TSLP)." (PMID 27558999, 2016). "Furthermore, high serum IL-33 was found to be related to severity of asthma, and IL-33 also caused airway remodeling in severe steroid-resistant asthma cases." (PMID 27310495, 2016). "IL-33 is a driver of type 2 inflammatory responses and is implicated in allergy and asthma." (PMID 27148268, 2016). "Moreover, a recent report documents a strong association between polymorphisms in IL-33 and hospitalization for asthma, an indicator of disease severity." (PMID 26214807, 2015). "Genomewide association studies implicate the ‘alarmin’ IL-33 in asthma, but its role in mast cell–ASM interactions is unknown." (PMID 25683166, 2015). "The potential involvement of IL-33 in the etiology of asthma has attracted considerable attention as a consequence of recent large-scale genome-wide association and polymorphism studies that link the genes for IL-33 (IL33) and its receptor (IL1RL1) to asthma susceptibility." (PMID 26214807, 2015). "Genomewide association studies have consistently implicated IL-33 as an asthma susceptibility gene." (PMID 25683166, 2015). "Higher levels of IL-33 have been detected in the lung of asthmatics, and genetic analyses have linked polymorphisms in the il-33 and st2 genes with allergic disease and asthma." (PMID 24551140, 2014). "In conclusion, low levels of 25(OH) Vit D might represent a risk factor for the development of concomitant asthma and rhinitis in children with allergic disease of the airways independently of IL-31/IL-33 Th2 activity." (PMID 25061262, 2014). "TG2-deficient mice revealed reduced IL-33 expression following asthma induction." (PMID 23496815, 2013). "Moreover, polymorphism of the ST2 and/or IL-33 genes was found in patients with asthma, atopic dermatitis, rhinitis and rhinosinusitis." (PMID 21494550, 2011). "At present, the role of IL-33/ST2 in studies using ST2-deficient mice is unclear as these mice are not protected in the ovalbumin-induced airway inflammation model but have attenuated inflammation in a short-term priming model of asthma." (PMID 21871091, 2011).